EZH2 (enhancer of zeste 2 polycomb repressive complex 2 subunit)
Diseases named in the same sentence as EZH2 in open-access papers (continued):
Sharing a sentence is not in itself a finding about the gene and the disease.
breast cancer (continued). "To this end, we have examined the effect of dual EZH2 and EHMT2 gene knockdown or enzyme inhibition in breast cancer cells." (PMID 26300989, 2015). "Therefore, the functions of EZH2 in breast cancer might be strictly regulated by lncRNAs." (PMID 26378045, 2015). "Agilent microarrays were used to perform gene expression profiling in MDA-MB-231 breast cancer cells after 24 h of treatment with the hit compound HKMTI-1-005, the EZH2 inhibitor GSK343 and EHMT2 inhibitor UNC0638." (PMID 26300989, 2015). "On the contrary, EZH2 knockdown in highly aggressive MDA-MB-231 cells decreased the metastatic burden and reduced the invasiveness of breast cancer cells at the metastatic site." (PMID 24742605, 2014). "miR-26a/b have also been reported to induce cell apoptosis by targeting MTDH, EZH2 and SLC7A11 in breast cancer cells and by targeting SODD in melanoma cells." (PMID 24565101, 2014). "With its reported Ki value of 24 nM against EZH2, compound 5 inhibited H3K27 methylation in the breast cancer cells with IC50s of ~50 nM." (PMID 25359765, 2014). "We demonstrate that some tumor types, such as neuroblastoma, have consistently high EZH2 activation, while pharyngeal cancer and subsets of glioblastoma, non-small cell lung cancer (NSCLC), and breast cancer have high HDAC4 activation." (PMID 24079712, 2013). "In particular, EZH2 activation is seen in luminal breast cancers and proneural GBM, while HDAC4 activation is seen in basal breast cancers and mesenchymal GBM." (PMID 24079712, 2013). "DZNep(3- Deazaneplanocin), a compound that disrupts the PRC2, effectively depletes EZH2, Suz12, and EED and inhibits H3K27me3 in breast cancer and AML cells." (PMID 23985559, 2013). "MiR-26a has been reported as a tumor suppressor microRNA in breast cancer, which is attributed mainly to targeting of MTDH and EZH2, however, the expression profile and therapeutic potential of miR-26a is still unclear." (PMID 23750239, 2013). "A metastatic breast carcinoma tissue microarray containing 110 metastatic lesions matched to 56 primary carcinomas on the first breast cancer microarray was used to determine the expression of both HOTAIR and EZH2 in the matched pairs." (PMID 23133536, 2012). "MiR-200c and miR-214 were previously reported to target BMI1 and EZH2, respectively, in studies that showed that miR-214 targets Ezh2 in skeletal muscle and embryonic stem cells and that miR-200c targets BMI1 in breast cancer stem cells." (PMID 21572997, 2011). "EZH2 is the core member of PRC2, which catalyses the trimethylation of H3K27, and we therefore investigated the expression of this gene in breast cancer." (PMID 20565864, 2010). "We investigated a mouse model that closely mimics breast cancer arising in BRCA1-mutation carriers to better understand the molecular mechanism of tumor progression and tested whether targeting of the Polycomb-group protein EZH2 would be a putative therapy for BRCA1-deficient tumors." (PMID 19709408, 2009). "This indicates that both EZH2 and its target gene CDKN1C can be used to predict breast cancer outcome." (PMID 19340297, 2009). "We have analysed the expression of EZH2 and BMI1 in a well-characterised dataset of 295 human breast cancer samples." (PMID 19099573, 2008). "Polycomb-group genes such as BMI1, EZH2 and SUZ12 have repeatedly been identified as adverse prognostic factors in breast cancer." (PMID 17573968, 2007). "Subsequent studies by Alison Hirukawa have further proven that EZH2 sustains the suppression of the FOXC1 gene through H3K27me3, thereby deactivating an anti-invasive transcriptional program driven by FOXC1 in Luminal B breast cancer." (PMID 40003882, 2025). "During breast cancer metastases, EZH2 was shown to be phosphorylated at T367 via p38 MAP kinase which induces cytosolic localization of EZH2 and further promotes EZH2 binding to many cytoskeletal regulators including vinculin which play critical role in cell migration and invasion." (PMID 40289112, 2025).
breast cancer (continued). "DZNep (3-deazaneplanocin A hydrochloride) is a S-adenosylhomocysteine hydrolase (SAAH) inhibitor depleting cellular levels of PRC2 components (EZH2, SUZ12, and EED), suppressing histone methylation, and inducing selective apoptosis in BC cell lines and primary mammary tumors." (PMID 40141248, 2025). "Importantly, the four most important hub genes RRM2, HMMR, EZH2, and CCNB1 appeared to play a significant role in various types of cancer such as non‐small cell lung carcinoma (NSCLC), liver and breast cancer." (PMID 39118438, 2024). "EZH2 physically interacts (without being catalytically active) with RelA/RelB in ER-negative basal-like breast cancer cells, leading to the expression of NF-kB target genes, namely IL-6, IL-8, and CSCL-1." (PMID 39767641, 2024). "As a result, EZH2 inhibition synergized with anti-PD1 therapy in prostate and breast cancer." (PMID 39133578, 2024). "We propose that low activity of EZH2 protein in EED-depleted HMLER cells promotes the transition of breast cancer cells into a metastable mesenchymal state without fully impairing MET." (PMID 39174513, 2024). "Moreover, EZH2 inhibitors can activate PPP2R2B expression, thus increasing breast cancer sensitivity to anti-HER2 therapy." (PMID 38976080, 2024). "This highlights the significance of the HIF-1/EZH2 signaling in the poor prognosis of ERα-negative breast cancer patients and the potential for drug combination to intervene in the ERα-FOXK2-HIF1β/EZH2 axis." (PMID 38911968, 2024). "Independent of PRC2, EZH2 regulates the shuttling of BRCA1 protein from the nucleus to the cytoplasm in basal-like breast cancer cells." (PMID 39682099, 2024). "The results confirmed that YPB and OPB peptides may decrease EZH2 recruitment to the promoters of target genes, such as PTENP1 and enhance anticancer activities reducing breast cancer cell proliferation and xenograft tumor formation." (PMID 38277283, 2024). "Based on the constructed IGRN between malignant cells at the invasive front of the TME and the immune cells of ER+ breast cancer patients, we found that a high expression of the transcription factors FOXA1 and EZH2 played a key role in driving tumor progression." (PMID 38254989, 2024). "Additionally, morphological and phenotypic features of CTH cells undergoing the giant cell cycle were detected upon HCMV infection, in addition to the potential involvement of Myc and EZH2 in both CTH cells and breast cancer biopsies." (PMID 39205199, 2024). "The axis of integrin α11-FAK-GLI-1/EZH2, formed in drug-resistant breast cancer cells, represents a shared positive feedback loop in both TAMR and ADR cells, which sustains the overexpression of EZH2 and ITGA11, thereby inducing drug resistance and CSC expansion." (PMID 38664825, 2024). "Similarly, EZH2 inhibitors abrogated the increase of H3K27me3 levels on the promoter of CCL2 to increase its transcription and secretion in breast cancer, which induced M2 macrophage polarization and recruitment in the TME." (PMID 39080807, 2024). "Unlike its enzymatic function in primary tumors, EZH2 promotes melanoma and breast cancer brain metastasis independent of its methyltransferase activity but relying on neutrophils." (PMID 39133578, 2024). "Studies in solid tumor mouse models have indicated that EZH2-expression is not essential for prostate and mammary tumor progression, and they critically question the safety of EZH2 inhibitors." (PMID 40135141, 2024). "Clinically, the use of EZH2 inhibitors in combination with IO represents a compelling strategy to remodel the TME, potentially overcoming immune evasion and enhancing therapeutic outcomes in breast cancer, mesothelioma, non-Hodgkin lymphoma and other cancers." (PMID 39830511, 2024).
breast cancer (continued). "Further bioinformatic analyses showed that SMYD2 expression, but not EZH2, is elevated in breast cancer metastases compared to primary tumors." (PMID 38296970, 2024). "In cancer, noncanonically EZH2 has been reported to promote tumorigenesis through the activation of oncogenes and inhibition of tumor-suppressor genes in prostate cancer and breast cancer." (PMID 37175580, 2023). "The cooperation between PAX2 and EZH2 has been confirmed to be abnormally expressed in ovarian cancer, whereas not reported in breast cancer." (PMID 36318256, 2023). "Phosphorylation of threonine 416 by cyclin-dependent kinase 2 promotes the recruitment of EZH2 at the target gene promoter, while methylation of lysine 307 (K307) by SMYD2 enhances the stability of EZH2 and promotes breast cancer cell proliferation, epithelial mesenchymal transition, and invasion." (PMID 37909018, 2023). "Thus, the EZH2-CCF-cGAS axis plays a crucial role in the secretion of inflammatory factors and tumor progression in breast cancer." (PMID 37543653, 2023). "Another inhibitor of EZH2 is 3-Deazaneplanocin A (DZNep), which alters methionine metabolism; it degrades EZH2 and inhibits H3K27 methylation, thereby inducing apoptosis in MCF7 breast cancer cells and HCT116 colorectal cancer cells." (PMID 37107631, 2023). "EZH2 exerts distinct non-histone methyltransferase roles in ER-negative and positive breast cancers." (PMID 36313363, 2022). "In addition, enhancer of zeste homolog 2 (EZH2) coactivates TGF-β signaling through the integrin β1 (focal adhesion kinase (FAK) pathway, to promote the bone metastasis of breast cancer." (PMID 36497209, 2022). "SUZ12 and EZH2 occupancy, along with E-box motifs and MYC occupancy, and H3K27me3 marks at the regulatory region of the ZNF148 locus provide a possible mechanism for MYC-induced repression of ZNF148 in breast cancer." (PMID 36207293, 2022). "Furthermore, EZH2 can interact with STAT3 and directly methylate STAT3, resulting in enhanced nuclear localization and chromatin of STAT3, thereby exacerbating breast cancer." (PMID 36313363, 2022). "In human breast cancer cell line MB-231 tumor-bearing mice, the combination of PARP inhibitor and EZH2 inhibitor or the simultaneous knockdown of PARP and EZH2 promoted the polarization of tumor-associated macrophages (TAMs) toward M2 and the generation of neovascularization in tumors." (PMID 36263120, 2022). "The TIMP-3 suppression in breast cancer cells is mediated by epigenetic silencing mechanisms, including the increased activity of the enhancer of zeste homolog 2 (EZH2) and class I HDACs, which is independent of promoter DNA hypermethylation." (PMID 35327559, 2022). "The role of EZH2 or EZH2 inhibitors in breast cancer development by affecting macrophage polarization has not been uniformly determined." (PMID 36038549, 2022). "To expand the investigation of EZH2’s effect on bone metastasis, we also established CRISPR/CAS9-mediated EZH2-knockout subclones in 4T1 mouse mammary tumor cells (4T1.KO #1 and #2) and examined their proliferation, migration, and invasion compared with those of the control 4T1 cells." (PMID 35538070, 2022). "To investigate the cytotoxic effect of combined EZH2 and ATM inhibition in human BRCA1-mutant breast cancer, we treated the human TNBC cell lines SUM149 (BRCA1-mutant) and CAL120 (BRCA1-wild type) with GSK126 and AZD1390, and analyzed cell viability using CellTiter-Glo and clonogenic survival." (PMID 35715861, 2022). "Next, we sought to investigate the protein expression correlation between EZH2 and KRT14 in TNBC patient samples from Breast Cancer Gene-Expression Miner v4.8 and discovered the protein expression of EZH2, and KRT14 is positively (p = 0.0018, r = 0.1) correlated with each other." (PMID 36446780, 2022).
breast cancer (continued). "In breast cancer, although high EZH2 and low H3K27me3 correlate with poor prognosis of estrogen receptor-positive (ER+) breast cancers, the methyltransferase EZH2 is not required for mammary cancer development." (PMID 36532284, 2022). "Collectively, our study uncovers a unique mechanism by which a transcriptional elongation factor demarcates the PRC2-mediated H3K27me3 domains in breast cancer cells and provides a molecular basis for therapeutically targeting CTR9-low breast tumors with EZH2 inhibitors." (PMID 35137163, 2022). "Current studies show that EZH2/NXPH4/CDKN2A axis can participate in regulating the proliferation and migration of non-small-cell lung cancer cells revealing a poor prognosis in the prognosis model of breast cancer." (PMID 36245981, 2022). "In addition, Chang found that in breast cancer, HIF-1α promotes EZH2 transcription and upregulates EZH2 expression by binding to HRE in the EZH2 promoter region." (PMID 35779185, 2022). "However, the levels of EZH2 and HDAC2 increased with the increase in the malignancy of breast cancer." (PMID 35892859, 2022). "One of their studies suggests that EZH2 promotes TGFβ signaling to promote breast cancer bone metastasis via activation of integrin β1-FAK signaling following intra-cardiac or tail vein inoculation of the breast cancer cells." (PMID 36446780, 2022). "Other studies that converge to the EZH2 role in breast cancer cisplatin resistance include the overexpression of SERPINA3 (serpin peptidase inhibitor, clade A, member 3), which reduces the sensitivity of TNBC cells to cisplatin and upregulates EZH2." (PMID 36230683, 2022). "Clinically applicable FAK inhibitors but not EZH2 methyltransferase inhibitors effectively inhibit breast cancer bone metastasis in vivo." (PMID 35538070, 2022). "The expression of EZH2 and G9a was considerably higher in breast cancer cells (MCF7, BT549, and MDA-MB-231) than in the noncancerous mammary epithelial cell (MCF10A), especially in the highly metastatic cells of the MDA-MB-231 cell line (left)." (PMID 35409271, 2022). "Here, we uncovered that in EZH2 high expressing breast cancer cells, FAK and integrin β1 bound to TGFβRI rather than TGFβRII and that FAK phosphorylated TGFβRI." (PMID 35538070, 2022). "In the presented study, we showed for the first time that EZH2 exacerbates breast cancer in non-canonical manner via STAT3-mediated signalings." (PMID 34335938, 2021). "As an oncogene, growing evidence has identified EZH2 was closely related to breast cancer development and progression through multiple molecular mechanisms, but no studies are related to the roles of CENPL, ISG20L2, MRPL3 and LSM4 in breast cancer." (PMID 34341433, 2021). "Here, we demonstrated that EZH2 exacerbated breast cancer in non-canonical manner by methylating STAT3." (PMID 34335938, 2021). "Although the canonical role of EZH2 in breast cancer has been vastly investigated, the non-canonical counterpart of EZH2 in this condition is much scarcely reported." (PMID 34335938, 2021). "MiR-26a directly targets several anti-apoptotic proteins, such as E2F Transcription Factor 3 (E2F3), myeloid cell leukaemia-1 (Mcl-1), metadherin (MTDH), enhancer of zeste homolog 2 (EZH2), and phosphatase and tensin homolog (PTEN) which are up-regulated in breast cancer." (PMID 33849540, 2021). "Considering the five hub genes, which were identified based on PPI networks and WGCNA, share the same signaling pathways during breast cancer progression, we conducted correlation analysis between the four novel hub genes (CENPL, ISG20L2, LSM4 and MRPL3) and EZH2." (PMID 34341433, 2021). "DZNep effectively decreases the expression of PRC2 proteins EZH2, SUZ12, and EED, as well as global H3K27me3 levels, leading to the reactivation of the PRC2-repressed genes and apoptosis in breast cancer cell line MCF-7 and colorectal cancer cell line HCT116, but not in normal cells." (PMID 34617019, 2021).
breast cancer (continued). "Furthermore, the overexpression of EZH2 is related to resistance to AR- and HER2-targeted therapy in prostate and breast cancers, respectively." (PMID 35186711, 2021). "In basal-like breast cancer, a significant increase in bromodomain-containing protein 4 (BRD4), lysine-specific demethylase 5B (KDM5B), and enhancer of zeste homolog 2 (EZH2) activities was detected in tumor cell populations after treatment with MEK and PI3K/mTOR inhibitors." (PMID 33597817, 2021). "Among these, many studies on EZH2 in breast cancer have been reported, but no studies are related to the roles of CENPL, ISG20L2, MRPL3 and LSM4 in breast cancer." (PMID 34341433, 2021). "Our study demonstrated that EZH2 exacerbates breast cancer through STAT3 signaling in non-canonical manner." (PMID 34335938, 2021). "Our results provide the direct evidence of the implication of non-canonical functions of EZH2 in breast cancer." (PMID 34335938, 2021). "We furthermore identified upregulation of the direct EZH2 target genes CNN3 and AKAP13, that are involved in chemotherapy resistance in colon cancer and breast cancer, respectively, and the genes MYO5A, AKT3 and SPECC1, which are implicated in the evasion of apoptosis." (PMID 33712646, 2021). "Finally, we provide a schematic representation of the biological role of the trans-cellular signaling pathway involving EZH2, STAT3, exo-miR-378a-3p, exo-miR-378d, DKK3 and NUMB in the regulation of breast cancer chemoresistance." (PMID 33823894, 2021). "Functionally, conditional ablation of EZH2 in the MTB/tetO-MIC model significantly delayed tumor onset and decreased the incidence of lung metastasis, showing that EZH2 is essential for progression of mammary tumors and metastasis." (PMID 33235291, 2021). "Moreover, the expressional levels of FOXC1 gene is negatively related with that of Polycomb group (PcG) genes, i.e., Bmi1, EZH2, and SUZ12, in breast cancer cells." (PMID 34167089, 2021). "EZH2 was also shown to function in the constitutive activation of NF-κB target gene expression in ER-negative basal-like breast cancer cells, with this function independent of its histone methyltransferase activity." (PMID 33804165, 2021). "In reference to reports, other EZH2 inhibitors like GSK343 and GSK236 are available to inhibit the tumor progression of various cancers as well, like glioblastoma, head and neck cancer and breast cancer." (PMID 34288823, 2021). "Here, we discover that dysregulation of both PTEN and EZH2 occurs in almost all breast cancers when compared to adjacent normal ducts, regardless of subtype." (PMID 33750924, 2021). "The correlation between EZH2 or NSD2 expression and molecular subtypes of breast cancer (BC)." (PMID 33665162, 2020). "We further demonstrated that EZH2-mediated epigenetic silencing of miR-29b or miR-30d reprogrammed the expression of LOXL4, which influenced cell proliferation and metastasis in the progression of breast cancer." (PMID 32754259, 2020). "Compounds 4a–n have been evaluated in p300, PCAF, SIRT1/2, EZH2 and CARM1 enzyme assays, and in NB4 human acute promyelocytic leukemia (APL), U937 AML, MCF-7 breast cancer and SH-SY5Y neuroblastoma cells, to determine their effects in cell cycle phases and apoptosis (sub-G1 peaks) induction." (PMID 32650558, 2020). "Such compounds were evaluated in p300, PCAF, SIRT1/2, EZH2 and CARM1 enzyme assays, and in NB4 APL, U937 AML, MCF-7 breast cancer and SH-SY5Y neuroblastoma cells, to determine their effects in cell cycle phases and apoptosis induction when used at 5 μM for 30 h." (PMID 32650558, 2020). "EZH2 and NSD2 protein expression in breast cancer (BC) and benign lesion tissues." (PMID 33665162, 2020). "We disclosed that ANCR-EZH2 interaction enhances CDK1 binding with EZH2 and increases the amount of pT345-EZH2, which results in EZH2 degradation and subsequently suppressing the oncogenesis and distant metastasis in breast cancer." (PMID 33308321, 2020).